ADAMTS1 (ADAM metallopeptidase with thrombospondin type 1 motif 1)
Diseases named in the same sentence as ADAMTS1 in open-access papers (continued):
Sharing a sentence is not in itself a finding about the gene and the disease.
Ureteral obstruction (1 paper, 2022). Obstruction of the flow of urine through the ureter. "Other ADAMTS proteins have previously been implicated in the pathogenesis of kidney fibrosis: higher expression of ADAMTS-1 was detected in the early course of fibrogenesis on mouse model of unilateral ureteral obstruction." (PMID 35328201, 2022).
viral myocarditis (1 paper, 2013). Myocarditis that is caused by an infection with a viral agent. "Our previous study of viral myocarditis using cDNA microarray analysis in the myocardium demonstrated that the expression of ADAMTS-1 increased significantly and the expression level correlated positively with the level of collagen deposition." (PMID 23977238, 2013). "To explore the relationship between IL-17A and ECM degradation from chronic viral myocarditis to DCM, we examined the expression of the ADAMTS-1 and MMPs/TIMPs proteins in the myocardium using western blotting." (PMID 23977238, 2013).
tumor (104 papers, 2006 to 2026). "The proteoglycan VCAN is the most notable substrate of ADAMTS1 and was identified as a modulator of adhesion loss, cell motility, and tumor progression." (PMID 39333870, 2024). "Like fibulin-1, ADAMTS-1 has also been implicated to participate in tumor processes with a dual function." (PMID 31508361, 2019). "We also need to mention the important increase of CD11b+ cells in the tumours in the Adamts1-deficient context." (PMID 30166561, 2018). "In conclusion, we have described here a promising and still little explored pro-inflammatory landscape, correlating with a halt of B16F1 tumours in Adamts1-deficient mice." (PMID 30166561, 2018). "Further investigations have revealed that epigenetic silencing through promoter hyper-methylation to be the key mechanism underlying ADAMTS1 suppression during tumour development." (PMID 30004416, 2018). "The current report reveals that the loss of ADAMTS1 in the host stroma leads to the impairment of tumor progression and development of metastasis." (PMID 27120788, 2016). "The ADAMTS family of extracellular metalloproteases, including ADAMTS1 and 9, has been widely implicated in remodeling of the tumor microenvironment during cancer development, growth and progression." (PMID 26675551, 2016). "For many family members, the dominant theme is tumor suppression as they show epigenetic silencing (ADAMTS1, 8, 9, 12 and 18) or mutational inactivation (ADAMTS15) in several cancer types." (PMID 26025392, 2015). "A significant association was observed between the ADAMTS1 methylation status, depth of tumor invasion and TNM stage." (PMID 25936341, 2015). "Nonetheless, ADAMTS-1 can also generate anti-angiogenic peptides through the digestion of thrombospondin-1 or endorse the recruitment of fibroblasts involved in tumor growth, an effect also associated to an increased deposition of collagen-1." (PMID 24457941, 2014). "Transition of the cell line LNCaP into its more malignant subline LNCaP-19 has previously been reported to result in loss of ADAMTS1 together with a more rapid tumor establishment." (PMID 20546609, 2010). "The transition of normal epithelial cells into tumour cells was associated with a loss of ADAMTS-1 immunostaining." (PMID 16495931, 2006). "Furthermore, the downregulation of ADAMTS1 was associated with the enhancement of tumours toward metastasis, while high levels were observed in CRPC." (PMID 38254687, 2024). "Moreover, the inhibition of ADAMTS1 affected in vitro EL attributes and, more importantly, caused a major halt of tumor progression in mice with alterations in vascular and endothelial parameters." (PMID 32230715, 2020). "For ADAMTS family members, metalloproteinase-related (ADAMTS1, 9) or angiogenesis-associated (ADAMTS1, 13) activity contributes to tumor development and progression, although some ADAMTSs inhibit or suppress cancer through metalloproteinase- or angiogenesis-independent activity (ADAMTS2, 12)." (PMID 27542224, 2016). "This suggests the possibility that the loss of ADAMTS1 function may be an important factor in tumor angiogenesis." (PMID 25936341, 2015). "Also in the human prostate, ADAMTS1 was downregulated in tumor tissue compared to benign tissue and decreased expression of ADAMTS1 was associated with increased angiogenesis and metastasis in androgen-independent tumors." (PMID 20546609, 2010). "Moreover, the expression level of ADAMTS1 is also known to be associated with tumor progression, and epigenetic modifications downregulate ADAMTS1 levels in many types of cancers, although a high expression level of ADAMTS1 is associated with cancer progression toward metastasis." (PMID 40878842, 2025). "ADAMTS1 functions dualistically: it can suppress tumor growth but also potentially support invasion via the Notch1-SOX2 pathway, whereas ADAMTS6 has unambiguously pro-oncogenic properties." (PMID 41304780, 2025).
tumor (continued). "In vivo, G1 reduced liver metastasis, increased E-cadherin, and decreased vimentin and proliferating cell nuclear antigen in primary tumor tissues and increased ADAMTS1 at the tumor edge." (PMID 40867252, 2025). "Elevated levels of ADAMTS1 can promote tumorigenic changes, including increased tumour cell proliferation, inhibition of apoptosis and altered angiogenesis." (PMID 40864881, 2025). "Our study revealed a significant increase in ADAMTS1 expression, particularly at the tumor margins, following G1 treatment." (PMID 40867252, 2025). "ADAMTS1 acts as a tumor metastasis promoter in OSCC, and L1CAM and EGFR are critical determinants regulated by ADAMTS1 when executing its prometastatic effect via EMT induction." (PMID 38263290, 2024). "Although roles for ADAMTS1 were suggested in promoting tumor invasion and metastasis in kidney, brain, and breast tumors, its role in proteoglycan proteolysis also has tumor-suppressive functions." (PMID 38263290, 2024). "This suggests that the catalytically active metalloproteinase domain of ADAMTS1 plays a critical role in ADAMTS1-induced tumor metastasis." (PMID 39333870, 2024). "To date, the literature suggests that ADAMTS-1 is the best-characterized tumor-promoting ADAMTS metalloprotease." (PMID 39682243, 2024). "In the immunohistochemical evaluation of ADAMTS-1, cytoplasmic marking was observed in tumor cells and rarely in the stroma, corroborating the findings of Silva and collaborators, who also detected ADAMTS-1 expression in cancer cells, including in the nucleus." (PMID 39682243, 2024). "In vivo, we also observed a significant reversal of increased tumor metastasis in ADAMTS1-overexpressing Caki-1 cells when these cells were engineered to express shRNA targeting VCAN or the EGFR." (PMID 39333870, 2024). "The matrix metalloprotease A disintegrin and metalloprotease with thrombospondin motifs 1 (ADAMTS1) was reported to be involved in tumor progression in several cancer types, but its contributions appear discrepant." (PMID 38263290, 2024). "In contrast, a tumour-suppressor role has also been reported for ADAMTS1 in breast cancer, related primarily in this study to the regulation of tumour vasculature." (PMID 38791926, 2024). "In this study, we provided a novel mechanism to address how ADAMTS1 regulates tumor metastasis in OSCC." (PMID 38263290, 2024). "In this study, we discovered a novel mechanism by which ADAMTS1 regulates tumor metastasis by inducing resistance to anoikis and invasion in RCC cells." (PMID 39333870, 2024). "ADAMTS1 acts as a tumour promoter in the genetic MMTV-PyMT model, with ADAMTS1 knockout mice having reduced tumour burden, metastasis, and prolonged survival, associated with enhanced leukocyte infiltration and cytotoxic immune signatures." (PMID 38791926, 2024). "In contrast to the conflicting role of ADAMTS1 in regulating tumor growth in different cancer types, investigations so far into the role of ADAMTS1 in cancer metastasis promotion have consistently associated increased cell motility with upregulated ADAMTS1." (PMID 38263290, 2024). "Despite there being lower ADAMTS1 expression in tumor tissues, a Kaplan–Meier plot showed that HNSCC patients from TCGA with ADAMTS1high tumors had shorter OS and DSS times compared to those with ADAMTS1low tumors." (PMID 38263290, 2024). "Our previous studies demonstrated that RCC invasion is significantly facilitated by ADAMTS1, highlighting the potential role of ADAMTS1 in driving anoikis resistance, a critical factor for tumor cell invasion and metastasis." (PMID 39333870, 2024). "In vivo, we also observed a significant reversal of increased tumor growth and cervical LN metastasis in ADAMTS1-overexpressed HSC-3 cells when these cells were engineered to express shRNA targeting L1CAM or EGFR." (PMID 38263290, 2024). "Tumor‐associated marker expression was significantly different among all cell types for MMP2, MMP7, MMP9, MMP12, ABHD5, ADAMTS1, AP‐1, and MGLL each with p < 0.001." (PMID 38037545, 2023).
tumor (continued). "The expression of ADAMTS1 was detected in NSCLC tissues and normal tissues using immunohistochemistry, which showed that the positive signal of ADAMTS1 in tumor tissues was significantly higher than that in adjacent normal tissues." (PMID 36947712, 2023). "As compared to IPMN-LGDs, IPMN-advanced neoplasia had higher hypermethylation frequency of candidate genes: ADAMTS1 (60% vs. 14%), BNC1 (66% vs. 3%), and CACGNA1G (25% vs. 0%)." (PMID 36803844, 2023). "In our study, we found that the expression of ADAMTS1 in NSCLC tumor tissues was significantly increased when compared with adjacent normal tissues, suggesting that the abnormal expression of ADAMTS1 correlates with NSCLC." (PMID 36947712, 2023). "Previous studies confirmed that ADAMTS1 is involved in inhibiting the proliferation, polarization and migration of tumor, affecting the quality of oocytes and embryonic development potential and promoting collagen production." (PMID 37363723, 2023). "HE staining and photographic results showed that overexpression of ADAMTS1 promoted the lung metastasis of tumor cells." (PMID 36947712, 2023). "In the NSCLC tumor metastasis model involving nude mice, overexpression of ADAMTS1 promoted EMT and lung metastasis of tumor cells." (PMID 36947712, 2023). "ADAMTS-1 can be expressed by tumor cells or tumor stromal cells and contributes to modifications in the tumor microenvironment by proteolytic or independent activity-dependent mechanisms." (PMID 36338393, 2022). "The ADAMTS1 transcriptomic level was significantly lower in tumor parts throughout different extents of lymph node (N0−N3) metastasis and pathological stages (stage I to IV), but were not lymph node metastasis or stage dependent." (PMID 35625488, 2022). "We evaluated the possible cooperation of candidate proteins with ADAMTS1 by assessing the expression correlation in the tumor of in-house and TCGA cohorts." (PMID 35625488, 2022). "Knockout of ADAMTS1 in mammary and melanoma cancer models resulted in reduced primary and secondary tumor burden, which correlated with increased infiltration of cytotoxic lymphocytes and increased expression of genes involved in antitumor immune reactions." (PMID 36010994, 2022). "In contrast, the shINHA hypoxia tumors showed increases in proteins including ADAMTS-1 (1.6 times) and Pentraxin-3 (1.3 times), indicating an anti- angiogenic profile in shINHA tumor cells as both have been demonstrated to be anti-angiogenic." (PMID 35654828, 2022). "Several studies have revealed that ADAMTS1 is down-regulated in a variety of tumors, as well as in GC tumor tissue." (PMID 33851708, 2021). "The MHCF1 unique mutations consisted of protein misfolding (Hsp-related genes) and acetylcholine receptor (Chrnb4 and Chrm5) genes that possibly act on cancer cell processes, and tumor suppressor (Adamts1 and Adamts5) and cell cycle (Aurkb and Bub1) genes." (PMID 34158541, 2021). "Using the NT/T paired sample data set from TCGA database, we confirmed decreased expression of ADAMTS1 in tumor samples compared with the non-tumor adjacent tissues (p = 0.000059) suggesting anti-tumor functions." (PMID 33805340, 2021). "This higher expression at initial stages of UVM would support our experimental data, as we observed a link between ADAMTS1 and stemness features, closely related with tumor initiation and early UVM progression." (PMID 32230715, 2020). "Common to the modulatory nature of these type of proteases, different reports presented a tumor suppressive activity for ADAMTS1 and, on the contrary, there is evidence of its protumorigenic properties." (PMID 33396280, 2020). "At this point, although vasculature displayed alterations, the blockade of tumor progression when ADAMTS1 was inhibited is still unsolved." (PMID 32230715, 2020). "The anti-tumor and anti-angiogenic effect displayed by ADAMTS1 has been described also in the context of GC, where a negative correlation between ADAMTS1 and VEGFA mRNA and protein expression was detected." (PMID 32456248, 2020).
tumor (continued). "These assays first revealed a significant induction of ADAMTS1 in tumor-spheres in comparison with monolayer cultures, suggesting its relevance during this process." (PMID 33396280, 2020). "Nonetheless, additional actions of ADAMTS1 contribute to tumor development, at least in this setting." (PMID 32230715, 2020). "Given the major blockade of tumor growth when ADAMTS1 was inhibited in these two models, we were unable to get relevant biopsies of some experimental groups." (PMID 32230715, 2020). "ApoA-I likely inhibits expression of Adamts1 in both tumor and stromal cells, though the mechanism remains to be elucidated." (PMID 32477466, 2020). "Next, we approached an in vivo tumor model to shed light on the role of ADAMTS1 in UVM plasticity and tumorigenesis." (PMID 32230715, 2020). "Although vasculature emerged affected in ADAMTS1-deficient tumors, the most relevant action implied the downregulation of endothelial CDH5 in tumor cells, in association with stemness markers." (PMID 32230715, 2020). "Instead, the positive correlation at earlier stages of the disease is in line with additional outcomes of this work, as we will discuss below, mainly suggesting the role of ADAMTS1 as a regulator of the plasticity of tumor cells." (PMID 33396280, 2020). "Recent study found that ADAMTS1 was required for a balanced immune cell repertoire and tumor inflammatory response via affecting lymphocyte and myeloid populations in the spleen and bone marrow." (PMID 33015704, 2020). "For instance, ADAMTS-1 can promote tumor growth and progression in both breast and ovarian cancers and can induce pathological angiogenesis through versican degradation." (PMID 31508361, 2019). "First, we noticed a decrease of Adamts1 in spleens of tumour-bearing mice, confirming its fine regulation during tumour growth." (PMID 30166561, 2018). "In fact, our study highlighted the alteration of immune infiltrates in B16F1 tumours in an ADAMTS1-dependent manner." (PMID 30166561, 2018). "Despite this, low ADAMTS1 expression in primary tumours compared to normal tissue is a common trend that can be correlated with disease progression." (PMID 30004416, 2018). "ADAMTS1 was initially characterized as an anti‐angiogenic molecule that exerts inhibitory effects on tumours." (PMID 29193730, 2018). "As happens with most of the members of the family, ADAMTS-1 behaves as protumor or tumor-suppressor metalloprotease depending on different factors." (PMID 28099917, 2017). "We found three down-regulated genes/proteins discriminating BIC-resistant cell lines from LNCaP cells: ADAMTS1, identified as a possible tumor suppressor and two cell adhesion proteins involved in PCa progression, NCAM2 and UTRN." (PMID 29216878, 2017). "The effect of a PPARδ ligand (GW501516) on ADAMTS1 expression mediates the function (e.g., anti-tumor activity) of PPARδ." (PMID 29212212, 2017). "Remarkably our results also support a pro-tumorigenic and pro-metastatic activity of ADAMTS1, and we provided for the first time the finding that ADAMTS1 originated in the stroma contributes more significantly than ADAMTS1 derived from tumor cells." (PMID 27120788, 2016). "As previous tumor studies have shown, the alteration of ADAMTS1 levels is accompanied by changes in the overall tumor structure and consistency, and specifically it has significant effects on the vasculature." (PMID 27120788, 2016). "A common finding has been the close connection of ADAMTS1 with neovascularization mechanisms, including its contribution to the acquisition of endothelial-like properties of some tumor cells." (PMID 27120788, 2016). "Full-length ADAMTS 1 has pro-tumor activity, whereas the fragmented protein has anti-tumor activity." (PMID 26916548, 2016). "Very interestingly, our recent results demonstrate that the basal expression of ADAMTS1 in stromal cells, such as endothelium and macrophage-related population, is induced in a tumor context." (PMID 27120788, 2016).